ICOS (inducible T cell costimulator)
Diseases named in the same sentence as ICOS in open-access papers (continued):
Sharing a sentence is not in itself a finding about the gene and the disease.
tumor (continued). "The functions of these two subsets were different: ICOS+ Tregs secrete much larger amounts of interleukin 10 (IL-10), a critical negative regulator in tumor escape; while ICOS- Tregs have a high capacity for TGF-β expression." (PMID 31777600, 2019). "Our previous study on mouse hematologic neoplasm cells indicated that a blockade of ICOS/ICOSL pathways in tumor cells led to the downregulation of IL-4 and IL-10, both of which have anti-inflammatory effects." (PMID 31143539, 2019). "So, the cytotoxic activity of IL-2-expanded NKs from ICOS-KO mice is decreased against tumor cells; which is remarkable when target cells expressing high levels of ICOS-L are used." (PMID 31283790, 2019). "ICOS positive CD4+ cells and tumor-associated Treg can be activated by ICOSL-expressed plasmacytoid DCs." (PMID 31143539, 2019). "An ideal combination of CD27 agonism with DC vaccination would be in boosting immune responses to low frequency antigens (e.g., tumor antigens) prior to co-stimulation through receptors with delayed expression and memory responses such as ICOS or 4-1BB." (PMID 30788290, 2019). "ICOS potentiates anti-tumor immunity mediated by CTLA-4 blockade in murine models of prostate cancer and melanoma." (PMID 30788290, 2019). "The CD28 family member ICOS is important in regulating the development and immunosuppressive function of Tregs and is an immunological hotspot in tumor immunology." (PMID 31355166, 2019). "A possible mechanism for this is that CTLA-4 blockade on tumor infiltrating lymphocytes leads to ICOS upregulation allowing binding by ICOS-L expressing cells." (PMID 30788290, 2019). "In this study, we found that blockade of ICOSL in vivo can in fact reduced Tregs in the tumor environment; however, careful dissection of the role of ICOS costimulation blockade on Tregs vs. effector T cells needs to be addressed." (PMID 30319662, 2018). "Sustained ICOS upregulation was associated with clinical benefit, with preclinical data confirming a role for ICOS signaling in optimal anti-tumor activity." (PMID 30400835, 2018). "ICOS+Tregs confer a strong suppressive capacity to influence other anti-tumor immune effector cells and have be a stronger predictor for clinical outcome than total Tregs in several tumors." (PMID 30319662, 2018). "Unexpectedly, IL-2/CD40 promoted a more regulatory phenotype in young tumor-associated CD8+ T cells, on account of increases in several regulatory markers, relative to PBS controls, specifically: CD39, A2AR, A2BR, ICOS, LAG-3, and PD-1." (PMID 30560130, 2018). "The expression of ICOS and its receptor was determined in blood tumor cell lines, and the results showed that both are highly expressed in FBL3, A20, and P388 cells, i.e., ICOS and its receptor are closely associated with hematologic tumors." (PMID 29316975, 2018). "As a result, expression of CD39, A2AR, A2BR, ICOS and LAG-3 was higher on tumor-associated CD8+ T cells from young, compared to elderly, IL-2/CD40-treated mice." (PMID 30560130, 2018). "On the other hand, an inhibitory, pro-tumor role has been attributed to ICOS signaling related to its function in Treg homeostasis, thus facilitating tumor immune evasion." (PMID 30687714, 2018). "Specifically, IL-2/CD40 reduced expression of several regulatory molecules (CD39, A2AR, A2BR, PD-L1, ICOS, and/or IL-10) on young tumor-infiltrating CD11c+ cells and CD4+ T cells, suggesting reduced suppressive activity." (PMID 30560130, 2018). "In summary, our results suggested that AML cells expressed ICOSL promote the expansion of ICOS+ Tregs in tumor environment, and ICOS+ Tregs further promote the proliferation of AML cells through secreting IL-10." (PMID 30319662, 2018). "Taken together, these data indicate that ICOS+ Tregs are a subset of recently activated Tregs as a result of contact with tumor self-antigens and are critical in maintaining self-tolerance." (PMID 30319662, 2018).
tumor (continued). "The CD39+ Treg population in the tumor, as well as in peripheral blood, showed significantly higher expression of ICOS compared to the CD39− Treg population in the same tissue." (PMID 30651930, 2018). "Other studies have depicted that altering ICOS signaling leads to modulated T cell response, which in turn is involved in infection clearance, tumor regression, and ameliorated pathology." (PMID 29892278, 2018). "Given the known role of ICOS in the development of follicular helper T cells, tumour-infiltrating lymphocytes (TILs) from the virus-treated tumours were characterized for the expression of Tfh lineage-specific markers (CD4+FoxP3−CXCR5+PD-1+ICOS+)." (PMID 28194010, 2017). "The role of ICOS in anti-tumour tumour efficacy of CTLA-4 blockade was confirmed by mouse studies, where therapeutic efficacy of CTLA-4 blockade was severely compromised in ICOS-deficient mice." (PMID 28194010, 2017). "Analysis of lymphocytes isolated from both NDV-injected and distant tumours confirmed the upregulation of ICOS on both CD4+FoxP3− and CD8+ cells." (PMID 28194010, 2017). "Accordingly, ICOS+ Tregs were found to localize near tumor pDCs, and the number of Tregs is directly correlated with the numbers of pDCs in the tumors." (PMID 29085361, 2017). "Another strategy to boost the efficacy of oncolytic NDV is to insert the ICOS gene (usually upregulated by viral infection) in order to induce higher levels of T-cell infiltration into the local tumor and distant tumor sites." (PMID 28944214, 2017). "This resulted in a marked increase in the ratio of both CD4+ and CD8+ ICOS+ Teff to ICOS+ Tregs in the tumor/lungs and periphery in mice receiving MVA-BN-HER2 treatment compared to control mice." (PMID 26961085, 2016). "The increase in ICOS on CD4+ T cells was most prominent within the tumor/lungs, but elevated levels were also detected in the periphery of the treated groups but not in the control, tumor-bearing mice." (PMID 26961085, 2016). "Low and high levels of LAG-3 and ICOS in each cell were scored using the median level of tumor infiltration by IC as a cut-off value." (PMID 27841362, 2016). "Analysis of CD8 T cells revealed that in the tumor/lungs ICOS expression showed the highest increases in MVA-BN-HER2-treated mice irrespective of CTLA-4 treatment." (PMID 26961085, 2016). "CD4+ T cells exhibited elevated ICOS expression in the tumor/lungs of untreated controls and all treatment groups compared to naïve, tumor-free mice." (PMID 26961085, 2016). "This shift in the ICOS+ Teff to ICOS+ Treg ratio was most pronounced at the tumor site, but it was also apparent in the spleen and blood." (PMID 26961085, 2016). "The expression profiles of the inducible T cell co-stimulatory (ICOS) molecule were of particular interest because this T cell activation marker is known to increase on CD4+ T cells within the tumor and periphery following anti-CTLA-4 treatment." (PMID 26961085, 2016). "FOXP3+ Tregs, which are mostly ICOS+ FOXP3+ Tregs in HCC tumour tissues, are the main immuno-suppressors in the liver carcinoma microenvironment." (PMID 27725696, 2016). "The percentage of ICOS+ Tfh cells was remarkably higher in tumor tissues (P = 0.002) than in para-tumor tissues, showing a similar pattern to that of peripheral blood." (PMID 26517519, 2015). "Specific stimulation of the coreceptor ICOS was reported to be capable of skewing Th17 cells to become IFNγ/IL-17-producing cells which have been revealed to be beneficial for tumour suppression." (PMID 26101460, 2015). "The MFI of GITR and ICOS are significantly higher in Tregs from tumours than in those from tumour-free liver tissue." (PMID 25961057, 2015). "The combination of anti-CTLA-4 antibody and ICOS activation, which was mediated by tumor vaccines engineered to express the ICOS ligand, enhanced anti-tumor response." (PMID 25859247, 2015).
tumor (continued). "In animal studies, ICOS was found to be necessary for optimal anti-tumor responses with anti-CTLA-4 and ICOS was shown to mediate PI3K-signaling to increase T-bet expression in the setting of anti-CTLA-4 therapy." (PMID 24883190, 2014). "In a human melanoma study, for example, CD4+Foxp3+ Treg cells infiltrating tumor tissue not only displayed upregulated expression of ICOS but also exhibited a more potent suppressive activity compared to those derived from circulating blood cells." (PMID 23874336, 2013). "A similar observation was made for ICOS expression in the tumor cells of one case each of typical NLPHL and THRLBCL as well as in five cases of THRLBCL-like NLPHL." (PMID 24244368, 2013). "If aberrant ICOS expression in the tumor cells occurred, only few ICOS+ TFH cells were found in the reactive microenvironment." (PMID 24244368, 2013). "While adjacent tissue showed limited ICOS signaling primarily between T/NK cells and DCs, the tumor environment displayed a more complex network with additional interactions involving macrophages and other immune cells, indicated by increased connection lines between cell populations." (PMID 41180156, 2025). "Tumor-associated DCs, especially pDCs, showed upregulated ICOSL expression compared to normal tissue, facilitating stronger interactions with T cells and notably promoting CD8+ T-cell activation through the ICOS–ICOSL pathway." (PMID 41180156, 2025). "Finally, ICOS-Fc can have direct effect on tumor cells expressing ICOSL by inhibiting tumor cell proliferation, migration, and metastatization which has been detected both in vitro and in vivo." (PMID 41471045, 2025). "ICOS exerted dual roles in tumor immunity by enhancing cytotoxic T cell activity while also promoting Treg–mediated immunosuppression, thus contributing to both anti– and pro–tumor effects." (PMID 40864806, 2025). "Importantly, TLSs in HPV-positive tumors were located closer to the tumor area and enriched in activated immune cells, including ICOS+ CD4 T- cells, memory T- cells, and CD21+ B- cells." (PMID 41254766, 2025). "Thus, it is critical to better understand relationships between ICOS with other immune checkpoints and tumor types to develop effective novel therapeutics targeting this pathway." (PMID 40297627, 2025). "Additionally, emerging evidence has demonstrated that ICOS expression in CAR-T cells correlates with superior anti-tumor efficacy." (PMID 40519924, 2025). "Additionally, higher levels of Treg cells were found in the primary tumor tissue, expressing elevated levels of costimulatory genes associated with immune checkpoints (CD27, ICOS, TNFRSF4, and TNFRSF18) and exhaustion markers (CTLA4 and TIGIT)." (PMID 40303346, 2025). "Mechanistically, Tregs express inhibitory molecules, including cytotoxic T-lymphocyte-associated protein 4 (CTLA-4), inducible T-cell costimulator (ICOS), glucocorticoid-induced TNFR-related protein (GITR), and OX40, both in tumors and tumor-draining lymph nodes." (PMID 41584838, 2025). "Low expression of IL‐11 in tumour cells was associated with significantly higher levels of leukocytes (CD45), T cells (CD3, CD4, CD8), T‐cell activation (CD44, CD25, ICOS, Tim3), dendritic cell activation, antigen presentation (CD11c, CD80, B2M, HLA‐DR) and macrophage (CD68) markers." (PMID 40673604, 2025). "Interestingly, CD4+ Tconv poorly expressed Tbet in TDLNs, whereas CD4+ Tconv co-expressing ICOS and Tbet were observed in tumors, suggesting that full engagement of the Th1 program occurs in the tumor microenvironment." (PMID 40460830, 2025). "In addition, proportions of ICOS+ 4-1BB+ T cells were significantly increased in tumor tissues being at least 3-times more abundant compared to both liquid samples." (PMID 41221283, 2025).
tumor (continued). "We found that Tbet+ICOS+ Th1-like CD4+ T cells expressed the highest level of PD-1 among tumor-infiltrating CD4+ Tconv, indicative of high tumor reactivity, and that in vivo treatment with 9D9 increased the proportion of PD-1+ CD4+ T cells producing IFNγ upon re-stimulation ex vivo." (PMID 40460830, 2025). "Tumor cells within these immune-enriched neighborhoods demonstrated PD-L1 positivity, and within the tumor area, we observed frequent interactions between PD-1+ T cells and PD-L1+ cells, as well as ICOS+ CD4+ T cells, indicating a more active, tumor-reactive phenotype." (PMID 41254766, 2025). "ICOS-ICOSL axis played a key role in the generation of effector T cells in tumor etiology." (PMID 40708008, 2025). "Thus, pDC infiltration correlated positively with ICOS+ Treg infiltration in the tumor tissue of GC patients." (PMID 38927922, 2024). "Adjacent T-cell-rich regions had higher levels of key proteins such as CD45RO and several immune suppressive factors (IDO1, VISTA, TIM-3, LAG-3 and ICOS), which may result in less T-cell expansion in regions close to the tumor." (PMID 39001353, 2024). "Surprisingly, ICOS co‐stimulation regulates tumor immunity at two different levels." (PMID 38506253, 2024). "Tregs may promote CRC tumor progression by downregulating ICOS and inhibiting the ICOS/ICOSL signaling pathway, inducing M2-type macrophage polarization." (PMID 39104717, 2024). "The expression of ICOS may therefore be correlated with clinical outcomes and prognosis, highlighting the importance of ICOS-L upregulation on tumor cells as a possible treatment approach." (PMID 39411143, 2024). "Remarkably, within the putatively exhausted tumor-infiltrating NK cell population, the coexpression of ICOS was increased by more than 15-fold compared to the same population in peripheral NK cells from CC patients, while the expression of 4-1BB was more than 10-fold increased." (PMID 39201462, 2024). "Moreover, ICOS knock-out mice do not respond well to anti-CLTA-4, suggesting a significant role for ICOS-signaling on effector T cell-mediated anti-tumour activity particularly when Tregs are blocked." (PMID 38440738, 2024). "Moreover, ICOS expression was considerably higher in tumor-infiltrating T cells than circulating T cells, particularly among conventional CD4+ T cells (p<0.001)." (PMID 38384469, 2024). "Traditionally, ICOS exhibits a dualistic role in tumor immunity." (PMID 39201462, 2024). "This is consistent with our findings that the increased level of ICOS expression predicts a lower malignancy of the tumor, which may be the reason for the good prognosis." (PMID 38506253, 2024). "Furthermore, ICOS-Fc treatment increases effector T cells and reduces regulatory T cells, inhibiting tumor cell metastasis." (PMID 39104717, 2024). "This study hypothesizes that host anti-tumor immune dysfunction may be due to excessive suppression of the ICOS/ICOSL pathway." (PMID 39104717, 2024). "Although ICOS’s role in tumor immunology has been extensively studied, its specific role and mechanism in CRC remain unclear." (PMID 39104717, 2024). "Thus, this work aims to evaluate the expression of the costimulatory receptors ICOS, 4-1BB, and OX-40 in exhausted peripheral and tumor-infiltrating NK cells from patients with CC." (PMID 39201462, 2024). "In advanced tumor stages, there was notably increased infiltration of ICOS+ Tregs." (PMID 38927922, 2024). "The exhausted population in the tumor dramatically overexpressed ICOS (15.4-fold change) compared to peripheral NK cells (PBMCs: 0.7673; TILs: 11.79; p < 0.0001), while 4-1BB was overexpressed 10.6-fold in TILs compared to PBMCs (PBMCs: 0.7073; TILs: 7.474; p = 0.0001)." (PMID 39201462, 2024). "ICOS has dual roles: it is a co-stimulatory receptor responsible for enhanced T cell responses to foreign antigens; in contrast, it promotes the immunosuppressive activity of Tregs and therefore exhibits pro-tumor activity." (PMID 39132150, 2024).
tumor (continued). "However, the prognostic impact of ICOS expression and pathway activation in different tumor types can vary, highlighting the complexity of ICOS biology, and immune dynamics in general, in cancer." (PMID 37593752, 2023). "Our data are in line with the role of CD137 as a relevant immunosuppressive molecule Treg-associated in the tumor microenvironment, different from what observed in periphery, and in agreement with an infiltrating CCR8+ICOS+ CD8+ Treg signature of disease progression found in NSCLC." (PMID 37898752, 2023). "Immune checkpoint therapy enhances the anti-tumor effect in the tumor microenvironment by regulating the function of T cells.In a preclinical drug experiment, it was found that the ICOS-ICOSLG pathway has a good clinical application prospect for immunotherapy of various tumors." (PMID 37842091, 2023). "ICOS may mediate the stimulation of tumor immunity, and its expression has been shown to be a survival predictor of HNSCC." (PMID 36983005, 2023). "There are several ways that ICOS inhibits T cells in the tumor microenvironment (TME)." (PMID 36855091, 2023). "ICOS expression is significantly upregulated in higher tumor grade in the METABRIC cohort." (PMID 38127899, 2023). "Tumor tissues with up-regulated ICOS expression also showed abnormal immune characteristics." (PMID 36855091, 2023). "Moreover, we observed cytoplasmic and sporadically nuclear tumor cell-intrinsic ICOS protein expression." (PMID 37259155, 2023). "However, the post-transcriptional and post-translational regulation of ICOS in tumor cells is beyond the scope of our study and needs further investigation." (PMID 37259155, 2023). "Uncertainty surrounds the function of ICOS in tumor immunity." (PMID 36855091, 2023). "On the other hand, ICOS could contribute to an-tumor immunity for the regulation of function and maintenance of Tregs." (PMID 38127899, 2023). "We found that ICOS‐ICOSL axis activation may influence tumor stages, overall survival (OS), and disease‐free survival (DFS)." (PMID 37850501, 2023). "Finally, the outcomes of ICOS are similar to the TCGA database, and its expression is beneficial to tumor treatment, but the results of its ligand are obviously different; the expression levels of ICOSL from TCGA were not related to DFS and OS." (PMID 37850501, 2023). "In both the TCGA and METABRIC cohorts, expression of ICOS is associated with molecular and clinical characteristics including age, tumor stage, estrogen receptor (ER) status, progestogen receptor (PR), HER2 status, and tumor grade." (PMID 38127899, 2023). "While the increase in ratios could reflect differences in tumor size or other factors, it suggests that ICOS agonism can provide therapeutic benefit despite the presence of ICOS-positive Treg cells." (PMID 37593752, 2023). "Here, we aimed to comprehensively investigate ICOS gene methylation at single CpG resolution and expression pattern with regard to transcriptional activity, patients’ survival and response to immunotherapy, and tumor microenvironment." (PMID 37259155, 2023). "Notably, we revealed that in CD28− T cells, ICOS plays conflicting roles in the periphery relative to the tumor site." (PMID 37898752, 2023). "In addition, anti-ICOS treatment of tumor-bearing mice increased IL-17A expression by CD4+ T cells in the lung." (PMID 36480166, 2023). "If confirmed, targeting ICOS in tumor cells by anti-ICOS mAbs might induce a second mode of action beyond T cell activation." (PMID 37259155, 2023). "Remarkably, in PD1+CD28− CD8+ T cells, ICOS was associated with highest polyfunctionality in periphery but was not beneficial at the tumor site, while it did not provide advantage to the CD28+ subgroup in any district." (PMID 37898752, 2023). "However, increasing evidence suggests the key role of ICOS in anti-tumor response induced by anti-CTLA4 therapy, such as ipilimumab or tremelimumab." (PMID 38127899, 2023).